STIL (STIL centriolar assembly protein)
Diseases named in the same sentence as STIL in open-access papers (continued):
Sharing a sentence is not in itself a finding about the gene and the disease.
cancer (continued). "STIL acts as an oncogene driver in a primary cilia-dependent manner in human cancer." (PMID 36531013, 2022). "Previous studies have suggested that STIL is critical for cancer cell migration." (PMID 36497260, 2022). "The phenotype and protein expression alteration due to STIL silencing could be reversed by IFT88 silencing in cancer cells." (PMID 35155425, 2022). "In summary, our results revealed the importance of STIL in pan-cancer." (PMID 35155425, 2022). "However, the function and mechanism of STIL in pan-cancer and how STIL regulates primary cilia in tumors still need to be explore." (PMID 35155425, 2022). "In pan-cancer levels, STIL showed consistent expression alteration with CDK1 and CCNB1." (PMID 35155425, 2022). "STIL is considered to be an oncogene whose expression is elevated in many types of cancers." (PMID 36497260, 2022). "The formation of aneuploidy could provide an evolving genome to help the cells adapt to the changing environment of cancer and escape normal checkpoints, revealing the cancer promotion function of STIL over-expression from the side." (PMID 35155425, 2022). "However, in READ and THYM, high STIL expression acted as a protective factor, indicating distinct heterogeneity prognostic values of STIL in different cancers." (PMID 35155425, 2022). "In summary, our results revealed the importance of STIL in cancers." (PMID 35155425, 2022). "STIL was widely up-regulated in multiple cancer types compared with adjacent normal tissues." (PMID 35155425, 2022). "Although many studies indicated that STIL dysregulation directly affected genomic instability and cell cycle of tumors, the potential molecular mechanisms and biological functions of STIL were still ambiguous in pan-cancer." (PMID 35155425, 2022). "Some studies have demonstrated that STIL is overexpressed in a variety of cancers." (PMID 33858425, 2021). "We used Oncomine datasets to analyze differential mRNA expression of STIL between normal and cancerous colon tissues from three different studies (Hong, Notterman, and Kaiser), which revealed a significant enrichment of STIL gene in cancer tissues." (PMID 34485108, 2021). "Furthermore, Cep131 overexpression contributes to excessive recruitment of STIL to the centriole, which stabilizes Plk4, leading to centrosome amplification and cancer development." (PMID 31358734, 2019). "Upregulation of STIL giving rise to aneuploidy could play a major role in providing an evolving genome to help the cells adapt to the changing environment of the cancer and escape normal checkpoints." (PMID 29352115, 2018). "STIL overexpression, which results in supernumerary centrosomes, could lead to cancer in inducing chromosomal instability." (PMID 29352115, 2018). "Therefore, increase in STIL expression leading to uncontrolled GLI1 de-repression likely represents a crucial step toward cancer progression." (PMID 29352115, 2018). "Thus, it is evident that STIL overexpression plays a multifaceted role in human cancers." (PMID 39727708, 2024). "Therefore, STIL expression alteration could regulate the cell cycle and eventually promote the occurrence of cancer." (PMID 35155425, 2022). "In summary, we herein show that STIL is significantly up-regulated in lung and many other types of cancers, and that its expression level is highly correlated with patient survival, implicating its potential application in cancer detection and as a prognostic marker." (PMID 35365182, 2022). "Moreover, STIL over-expression is correlated with increased metastatic potential in cancers." (PMID 35155425, 2022). "STIL could regulate the cancer cell cycle through primary cilia." (PMID 35155425, 2022). "Furthermore, high STIL expression patients showed a worse prognosis in most cancer types." (PMID 35155425, 2022). "Targeting STIL might be a novel therapeutic approach for cancers." (PMID 35155425, 2022).
cancer (continued). "Of course, though the impact of mutation and DNA methylation in STIL expression was not noticeable, we still cannot ignore their existence because the role of these epigenetic characterizations was different in various cancer types." (PMID 35155425, 2022). "Interestingly, STIL upregulation has been found in many types of cancers." (PMID 35365182, 2022). "All in all, STIL was an crucial molecular marker and might be a novel targeted therapy for cancer." (PMID 35155425, 2022). "As a potentially pivotal gene, STIL might be a novel therapeutic target for cancers." (PMID 35155425, 2022). "Furthermore, the patients with high STIL expression showed worse outcomes in pan-cancer." (PMID 35155425, 2022). "However, the molecular mechanisms and biological functions of STIL in cancers remain ambiguous." (PMID 35155425, 2022). "Moreover, STIL expression was highly correlated with several hall-mark cancer pathways, including Mitotic spindle, G2M checkpoint, and E2F targets pathways across 33 cancer types, suggesting STIL played a stable molecular function in pan-cancer." (PMID 35155425, 2022). "Therefore, increase in STIL expression likely represents a crucial step toward cancer progression." (PMID 34485108, 2021). "STIL could also have an indirect effect on cancer, as a downstream effector of PLK4." (PMID 29352115, 2018). "In addition, the involvement of STIL in cancer shows that the result of spindle defects can be vastly different depending on the stage of development and the tissue involved that probably is partly due to differential responses to mitotic checkpoint mechanisms." (PMID 29352115, 2018). "Similarly, overexpression of genes such as STIL could act as oncogenes and lead to cancer by promoting spindle defects, although direct evidence of a link between oncogene activation and spindle misorientation is lacking." (PMID 29352115, 2018). "Inhibition of STIL oligomerization through its CCD and/or IDR is a promising new potential target for cancer therapy." (PMID 37834064, 2023). "The similar results between STIL mRNA expression and CNV were also observed across pan-cancer cell lines from the CCLE dataset, suggesting that STIL CNV also played an important role in regulating STIL expression level." (PMID 35155425, 2022). "As a novel substrate of PLK4, Cep131 is phosphorylated to facilitate recruitment of SCL-interrupting locus protein (STIL) to the centriole, leading to centrosome amplification and cancer development." (PMID 33663596, 2021). "STIL, being a critical factor in cell cycle machinery, its downregulation resulted in aberrant cell cycle and reduced proliferation in HT29 cancer cells." (PMID 34485108, 2021). "However, that patients whose STIL mutation is clearly associated with centrosome amplification could be at risk of developing cancer cannot be ruled out." (PMID 29352115, 2018). "Disappearance of indirect connections between STIL and CDK1 can be interpreted as loosening the control over several important cyclins (CCNA2 and CCNE1) and the key cell cycle protein CDK1 in cancer." (PMID 29370181, 2018). "The detection results of lactate production revealed that overexpression of STIL significantly increased lactate production in HCC cells relative to the control group, while the addition of 2‐DG in oe‐STIL‐treated cancer cells brought lactate production back to the level of the control group." (PMID 39718123, 2025). "However, in co-immunoprecipitation (co-IP) experiments using crude neuronal lysates as well as synaptosomal fractions, little binding between endogenous STIL and ARHGEF7 was detected, while we have previously shown binding in cancer cells." (PMID 39851490, 2025). "STIL promotes the development of many cancers; however, there is no detailed investigation of STIL in BC." (PMID 36497260, 2022).
cancer (continued). "In individual cancer (including ACC, BRCA, KICH, KIRP, LIHC, LUAD, and PAAD), STIL expression also increased with advanced pathological stage, suggesting that STIL may promote the progression of these cancers." (PMID 35155425, 2022). "Interestingly, excess STIL activates the EMT pathway, and subsequently enhances cancer cell migration and invasion." (PMID 35365182, 2022). "Another aspect of STIL, which has not been explored, is its role in Shh signaling-mediated stem cell maintenance in cancer." (PMID 34485108, 2021). "In the GSE13507 dataset, we also observed that the overall survival (OS), cancer-specific survival (CSS), progression-free survival (PFS), and recurrence-free survival (RFS) of patients with higher STIL expression showed poor outcomes than that of patients with lower STIL expression." (PMID 37101292, 2023). "Importantly, we demonstrate that STIL plays a versatile role in multistage tumorigenesis through the HIF1α-STIL-FOXM1 axis, and therefore may serve as a promising target for cancer therapy." (PMID 35365182, 2022). "Besides, STIL expression was positively correlated with the Mitotic spindle, G2M checkpoint, and E2F targets pathways across 33 cancer types, suggesting that the molecular mechanisms of STIL in cancers were stable and did not change with cancer type." (PMID 35155425, 2022). "This further suggests that STIL may not play a role in cancer cell migration and thus metastasis in concordance to tissue array observation." (PMID 34485108, 2021). "Importantly, STIL expression is strongly related to the infiltration of immune cells, the expression of several immune checkpoints, and the survival benefit of ICI treatment and chemotherapeutic drugs, shedding light on further exploring novel immune-based combination therapies for cancers." (PMID 36899391, 2023). "Genomic analyses of cancer cell line data reveal a negative correlation between FBXW7 expression and aneuploidy, as well as a positive correlation between FBXW7 and STIL expression at the mRNA level." (PMID 41453690, 2025).
adenocarcinoma (1 paper, 2013). A common cancer characterized by the presence of malignant glandular cells. "Furthermore, the overexpression of STIL is associated with metastasis of adenocarcinomas of the lung, breast, ovary, prostate and colon." (PMID 23472065, 2013).
STIL also shares sentences with these, for which no sentence is quoted: holoprosencephaly (3 papers); acute lymphoblastic leukemia (2); nasopharyngeal carcinoma (2); autism (1); breast tumors (1); ciliopathies (1); Fanconi anemia (1); glioma (1); leukemia (1); Li-Fraumeni syndrome (1); Lissencephaly (1); lung squamous cell carcinoma (1); metastatic cancers (1); nervous system disorder (1); non-small cell lung carcinoma (1); pancreatic adenocarcinoma (1); rectal cancer (1); serous ovarian carcinoma (1); small cell lung carcinoma (1).